GNG4 (G protein subunit gamma 4)
Diseases named in the same sentence as GNG4 in open-access papers (continued):
Sharing a sentence is not in itself a finding about the gene and the disease.
cancer (continued). "In the present study three key genes in UCEC include Endoglin, GNG4 and epithelial cell transforming 2 (ECT2) identified, therefore enhancing our comprehension of UCEC and broadening insights into the prognosis for this cancer type." (PMID 39552710, 2024). "According to these results, GNG4 may be employed as a biomarker to predict the immunotherapy response in BLCA b, as well as in other cancer types." (PMID 35456499, 2022).
GNG4 also shares sentences with these, for which no sentence is quoted: colon adenocarcinoma (3 papers); adenoid cystic carcinoma (1); asthma (1); Castleman disease (1); childhood asthma (1); human papillomavirus infection (1); lymphoma (1); neurodegenerative disease (1).